NLRX1 (NLR family member X1)
Diseases named in the same sentence as NLRX1 in open-access papers (continued):
Sharing a sentence is not in itself a finding about the gene and the disease.
inflammatory bowel disease (9 papers, 2018 to 2025). A spectrum of small and large bowel inflammatory diseases of unknown etiology. "Indeed, dysfunctional NLRX1 has been associated with several autoimmune diseases including lupus, multiple sclerosis, and inflammatory bowel disease and is expressed in a multitude of cell and tissue types associated with these maladies." (PMID 31681307, 2019). "Similar to our finding, a prior study reported reduced NLRX1 expression in a mouse model of inflammatory bowel disease during Dextran Sulfate Sodium (DSS) challenge." (PMID 39875919, 2025). "In inflammatory bowel disease (IBD) models, NLRX1 deficiency led to a metabolic switch towards aerobic glycolysis, which resulted in enhanced inflammation." (PMID 33525671, 2021). "Also, Nlrx1-/- mice show exacerbated severity of inflammatory bowel disease (IBD) and increased incidence of colitis-associated colonic cancer." (PMID 31052241, 2019). "In addition, NLRX1 regulated glutamine metabolism as NLRX1 KO mice showed increased glutamine utilization and interestingly glutamine supplementation alleviated the severity of inflammatory bowel disease in mice." (PMID 33344269, 2020).
autoimmune disease (6 papers, 2018 to 2023). A disorder resulting from loss of function or tissue destruction of an organ or multiple organs, arising from humoral or cellular immune responses of the individual to their own tissue constituents. "NLRX1 is a negative regulator of immune signaling and metabolic pathways implicated in host responses to microbes, cancers, and autoimmune diseases." (PMID 32956405, 2020). "Studies have shown the association between NLRX1 and autoimmune diseases such as SLE, RA, and IBD." (PMID 37122709, 2023). "Overall, research on NLRX1 in the field of autoimmunity is rapidly developing, yet its exact mechanisms in autoimmune diseases remain to be fully elucidated." (PMID 37122709, 2023). "In summary, these studies provide a perspective on targeting NLRX1 in not only pathogen infection but also autoimmune diseases." (PMID 34697412, 2022). "NLRX1 is considered to be an emerging metabolic regulator that can control cancer cell metabolism and has the potential to alleviate the symptoms of autoimmune diseases as well." (PMID 33525671, 2021). "More recently, NLRX1 has also gained interest in the field of cancer and metabolism where NLRX1 functions to attenuate overzealous inflammation in various inflammatory and autoimmune diseases." (PMID 33344269, 2020). "Particular attention is attributed to NLRX1, which attenuates inflammatory pathways in multiple infectious and autoimmune diseases." (PMID 33344269, 2020). "Given the importance of NLRX1 in LAP and inflammation, our findings raise the possibility that NLRX1 may be implicated in the development of autoimmune disease and tumor by regulating LAP induction." (PMID 30559741, 2018). "However, inappropriate activation of inflammasomes, including NLRP3 and NLRX1, is closely related to multiple autoimmune diseases, such as SLE, RA, and other inflammatory diseases, which is well summarized and discussed in two recently published review articles." (PMID 37122709, 2023). "One consistency is that many studies have shown that NLRX1 attenuates diseases, including chronic obstructive pulmonary disease (COPD), autoimmune diseases, and cancer." (PMID 34697412, 2022).
chronic obstructive pulmonary disease (5 papers, 2021 to 2024). A chronic and progressive lung disorder characterized by the loss of elasticity of the bronchial tree and the air sacs, destruction of the air sacs wall, thickening of the bronchial wall, and mucous accumulation in the bronchial tree. "Decreased NLRX1 expression in chronic obstructive pulmonary disease patients is linked to pulmonary disease severity and poor prognosis." (PMID 38671928, 2024). "Our previous study reported the pathogenic role of NLRX1, which may contribute to the development of chronic obstructive pulmonary disease (COPD)." (PMID 34087956, 2021). "Similarly, expression of NLRX1 was reduced in aneurysm-induced brain injury and in chronic obstructive pulmonary disease (COPD)." (PMID 35651602, 2022). "From our previous study that established the pathogenic role of NLRX1 in chronic obstructive pulmonary disease (COPD) for which aging is an important risk factor, we questioned what functional significance NLRX1 may have in cellular senescence and the biology of lung aging." (PMID 34087956, 2021).
colorectal cancer (5 papers, 2014 to 2023). A primary or metastatic malignant neoplasm that affects the colon or rectum. "Nlrp3−/−, Nlrp6−/−, Nlrc4−/−, Nlrp1−/−, Nlrx1−/− and Nlrp12−/− mice show increased susceptibility to inflammation-induced colorectal cancer as compared to wild-type mice." (PMID 31186453, 2019). "In support for this, our in vivo studies highlight the importance of NLRX1 in colorectal cancer susceptibility." (PMID 24867956, 2014). "Similarly, in vivo models have shown that NLRX1 was associated with the control of a number of diseases, including multiple sclerosis, colorectal cancer and ischemia-reperfusion injury." (PMID 37574163, 2023). "In DSS/AOM and APCmin/+ murine models of colorectal cancer (CRC), NLRX1 was shown to supress the development of CRC, as deletion of NLRX1 resulted in increased susceptibility, mortality and tumor burden." (PMID 37574163, 2023). "In a murine model of colorectal cancer induced by azoxymethane, NLRX1−/− mice developed fewer tumors than wild type mice." (PMID 24867956, 2014). "In addition to our current findings, prior studies have also evaluated NLRX1 in cancer utilizing either xenograft models or models of inflammation driven colorectal cancer." (PMID 27105514, 2016).
HIV-1 infection (5 papers, 2018 to 2025). The type species of lentivirus and the etiologic agent of acquired immunodeficiency syndrome (AIDS). "So far one study has proposed a role for NLRX1 in human DCs, showing that NLRX1 promotes HIV-1 infection in multiple cell types including human primary macrophages and DCs." (PMID 30344524, 2018). "NLRX1 can block STING-TBK-mediated antiviral responses in HIV-1 infection and support the early antiviral response by regulating IRF-1 abundance post-transcriptionally The NLRX1 gene can increase autophagy and reduce inflammatory responses." (PMID 41463370, 2025). "A recent study demonstrated that two mitochondria-localized proteins (NLRX1 and FASTKD5) mediate OxPhos upregulation during HIV-1 infection of CD4+ T cells, promoting viral replication, thus uncovering a novel and interesting regulatory axis for therapeutic targeting against HIV-1 infection." (PMID 35205318, 2022).
Autoimmunity (4 papers, 2019 to 2021). The occurrence of an immune reaction against the organism's own cells or tissues. "NLRX1 has been implicated in many infectious and sterile inflammatory diseases; however, its connection to autoimmunity and cancer biology is raising NLRX1 as a strong therapeutic target." (PMID 34768828, 2021). "Nlrx1 (NOD9) is a critical regulator of immune signaling, metabolism, autophagy, and cell death in response to viruses, bacteria, eukaryotes, cancer, autoimmunity, and tumors." (PMID 32956405, 2020). "We provide evidence that expression of NLRX1 in the innate immune compartment is sufficient to suppress T cell–mediated autoimmunity." (PMID 31525189, 2019). "In summary, our findings highlight the importance of NLRX1 in controlling the early stages of CNS inflammation and preventing the onset of spontaneous autoimmunity." (PMID 31525189, 2019).
brain injury (4 papers, 2020 to 2022). Acute and chronic (see also brain INJURIES, CHRONIC) injuries to the brain, including the cerebral hemispheres, CEREBELLUM, and brain STEM. "The anti-inflammatory function of NLRX1 has also been demonstrated in sterile CNS inflammation, such as that in traumatic brain injury." (PMID 32151250, 2020).
breast carcinoma (4 papers, 2016 to 2023). "Besides pathogen-induced mitophagy, NLRX1 also regulates mitophagy in mammary tumors, since NLRX1 upregulation in aggressive metastatic breast cancer cell lines is associated with higher metastatic potential." (PMID 33525671, 2021). "Even within a specific type of cancer, such as breast cancer and hepatocellular carcinoma, the expression of NLRX1 can vary based on the subtype and aggressiveness of the specific tumor or cell line." (PMID 37342194, 2023). "In the context of cancer, NLRX1 plays a role in TNF induced mitochondria-lysosomal crosstalk in mammary tumors." (PMID 31681307, 2019). "Indeed, several studies have shown NLRX1 is protective against colon cancer, histiocytic sarcoma, hepatocellular carcinoma, and ER/PR+ breast cancer through signaling pathways including but not limited to NF-κB, MAPK, AKT, and TNF-induced apoptosis." (PMID 37342194, 2023). "NLRX1 modulates mitochondrial functions to suppress tumorigenesis in solid tumors, but may facilitate aggressive breast cancer metastasis." (PMID 31681307, 2019). "Conversely, NLRX1 has been found to augment tumor progression in an AOM-only model of colon cancer, HPV-induced head and neck squamous cell carcinoma, and ER/PR- breast cancer where it increases disease burden and promotes aggressive phenotypes." (PMID 37342194, 2023). "Recent evidence suggested that upregulated expression of NLRX1 may synergistically regulate metabolism and autophagy for highly invasive growth of the autophagy addicted MDA-MB-231 breast cancer cells." (PMID 27829861, 2016).
colon carcinoma (4 papers, 2016 to 2023). "Studies have found NLRX1 in IECs to have a tumour suppressor role, and human colon tumours also have reduced NLRX1 expression." (PMID 34854889, 2021). "In the xenograft study, nude mice were injected with RKO colon carcinoma cells, where NLRX1 was either stably knocked down or overexpressed." (PMID 27105514, 2016).
gastric cancer (4 papers, 2017 to 2023). A primary or metastatic malignant neoplasm involving the stomach. "NLRX1 was found to be associated with risk of gastric cancer in the Chinese population." (PMID 28960882, 2017). "For example, high NLRX1 expression positively correlated with HIV-1 viremia in patients, or conversely low expression was associated to low prognosis of hepatocellular carcinoma and gastric cancer." (PMID 35651602, 2022).
hepatocellular carcinoma (4 papers, 2018 to 2026). A malignant tumor that arises from hepatocytes. "While NLRX1 has been recognized as a tumor suppressor in colorectal and hepatocellular carcinomas, it appears to act as a tumor promoter in breast and head and neck cancers." (PMID 42088413, 2026). "Consistent with our studies in Pan02 cells, NLRX1 also increased cell death and decreased migration in vitro in two hepatocellular carcinoma cell lines." (PMID 37342194, 2023). "In several of these same models and a model of hepatocellular carcinoma, NLRX1 also limits AKT signaling to protect against disease." (PMID 37342194, 2023). "A previous study identified fragment 556–974 of the human NLRX1 protein as being responsible for the protective phenotypes in hepatocellular carcinoma models, but further work is needed to elucidate how NLRX1 is able to function differently in different models and scenarios." (PMID 37342194, 2023). "This study was performed to investigate the role of nucleotide-binding oligomerization domain (NOD)-like receptor X1 (NLRX1) in regulating hepatocellular carcinoma (HCC) progression." (PMID 29482578, 2018).
influenza (4 papers, 2015 to 2025). An acute viral infection of the respiratory tract, occurring in isolated cases, in epidemics, or in pandemics; it is caused by serologically different strains of viruses (influenzaviruses) designated A, B, and C, has a 3-day incubation period, and usually lasts for 3 to 10 days. "In addition to the regulation of NLRX1 function by FAF1 during influenza infection, NLRX1 driven antiviral signaling can also be attributed to the attenuation of viral protein translation." (PMID 40356929, 2025). "Similarly, NLRX1−/− mice infected with influenza displayed impaired type I IFN response, increased viral replication in the lung, and increased airway hyperreactivity." (PMID 33525671, 2021). "Additionally, NLRX1 is a regulator of inflammation, autophagy, and ROS production in response to viral and bacterial pathogens ranging from Chlamydia to influenza." (PMID 26714018, 2015). "NLRX1 and PB1-F2 interactions were confirmed using both confocal microscopy and coimmunoprecipitation following influenza infection in HEK293T cells and human airway epithelial (A549) cells." (PMID 40356929, 2025). "In macrophages, NLRX1 promotes type I IFN production and protects macrophages from influenza-induced apoptosis by binding to the viral PB1-F2." (PMID 33525671, 2021). "In contrast, Nlrx1-/- mice have reduced interferon responses during influenza independent of MAVS interactions." (PMID 26367386, 2015). "For example, NLRX1 has been identified as a regulator of mitochondrial antiviral immunity through interference with RIG-I-MAVS and TRAF6-NF-kB signaling to attenuate inflammation during Sendai virus and influenza infections and LPS induced shock." (PMID 26367386, 2015).
ischemia (4 papers, 2019 to 2025). A hypoperfusion of the BLOOD through an organ or tissue caused by a PATHOLOGIC CONSTRICTION or obstruction of its BLOOD VESSELS, or an absence of BLOOD CIRCULATION. "We previously demonstrated that NLRX1 deletion increased infarct size in isolated mouse hearts subjected to ischemia–reperfusion injury (IRI); however, underlying mechanisms are yet to be identified." (PMID 40536683, 2025). "Research on intestinal ischemia–reperfusion injury has discovered that NLRX1 regulates mitophagy and inhibits apoptosis." (PMID 38107093, 2023). "In this model, the effect of NLRX1 on oxidative stress was only noticeable after ischemia, which is accompanied by a strong influx of inflammatory cells and necrotic debris." (PMID 30908533, 2019). "Finally, because it is known that protection against cardiac IRI is critically dependent on duration of ischemia, i.e. degree of infarction, effects of NLRX1 were examined for short and long ischemia duration." (PMID 33362773, 2020). "Without NLRX1 present, the energy sensor AMPKα is continuously activated in the heart, thereby preventing mTOR and RISK pathway activation during early reperfusion of the ischemic hearts, contributing to the increased sensitivity of the heart to ischemia–reperfusion injury." (PMID 40536683, 2025). "However, we cannot further differentiate whether these changes in p-Akt with NLRX1 ablation are specific for severe ischemia only, and not for mild ischemia, because Akt was not determined following mild ischemia." (PMID 33362773, 2020). "NLRX1 KO significantly increased IRI (infarct size from 63% to 73%, end-diastolic pressure from 59 mmHg to 75 mmHg, and rate-pressure-product recovery from 15% to 6%), following severe, but not mild, ischemia." (PMID 33362773, 2020).
lung diseases (4 papers, 2021 to 2024). "In earlier studies, NLRX1 was shown to be associated with various pulmonary diseases, such as influenza A virus infection, invasive pulmonary aspergillosis, and COPD, as well as with aging." (PMID 36859435, 2023). "The antiviral protein NLRX1 was another interesting member of this cluster that was significantly downregulated compared to the majority of patients in the other lung diseases." (PMID 37519267, 2023). "In conclusion, our study provides evidence that NLRX1 plays as a crucial regulator of cellular senescence and offers an in vivo murine model system that can be useful to elucidate the intersection of aging biology and the pathobiology of lung diseases." (PMID 34087956, 2021).
multiple sclerosis (4 papers, 2019 to 2023). A progressive autoimmune disorder affecting the central nervous system resulting in demyelination. "We generated a novel, spontaneous, and rapidly progressing mouse model of multiple sclerosis (MS) by crossing myelin-specific T-cell receptor (TCR) transgenic mice with Nlrx1−/− mice." (PMID 31525189, 2019). "Besides this antiinflammatory role, NLRX1 is also neuroprotective in mouse model of multiple sclerosis." (PMID 31892810, 2019). "NLRX1 is a guardian protein that inhibits the inflammatory response of glial cells within the central nervous system and prevents the onset of a spontaneous multiple sclerosis–like disease in mice." (PMID 31525189, 2019).
acute myocardial infarction (3 papers, 2020 to 2025). Necrosis of the myocardium, as a result of interruption of the blood supply to the area. "NLRX1 was decreased in patients with acute myocardial infarction, and we also observed decreased NLRX1 protein level in post-IR mouse and pig heart." (PMID 40536683, 2025). "For example, NLRX1 alleviates hypoxia-induced apoptosis and inflammation during acute myocardial infarction, or acts as an anti-inflammatory agent in cerebral ischemia reperfusion injury via decreasing pro-inflammatory cytokine production." (PMID 33525671, 2021). "As NLRX1 seems to be downregulated in the heart from acute myocardial infarction (AMI), the activation of NLRX1 by novel compounds may offer new therapeutic option to protect patients from myocardial infarction." (PMID 33362773, 2020).
experimental autoimmune encephalomyelitis (3 papers, 2020 to 2025). An autoimmune demyelinating disease of the central nervous system that is produced experimentally in animals by the injection of homogenized brain or spinal cord in Freund's adjuvant. "Recently, a fusion protein of an NOD-like receptor family member X1 (NLRX1) and blood–brain barrier-permeable peptide dNP2 treated experimental autoimmune encephalomyelitis in mice and a peptide that selectively recognizes the CNS was used for targeted drug delivery to the CNS in mice." (PMID 32429225, 2020). "Since NLRX1 deficient mice had more severe experimental autoimmune encephalomyelitis (EAE) than wild-type mice 31, and dNP2 showed remarkable protein delivery efficiency in T cells, we hypothesized that exogenous administration of NLRX1 proteins might be able to control EAE disease progression." (PMID 32194859, 2020). "Using multiple experimental autoimmune encephalomyelitis (EAE) models, we discovered that NLRX1 protects neurons in the anterior visual pathway from inflammatory neurodegeneration." (PMID 39875919, 2025). "In this study, we demonstrate that a fusion protein of NOD-like receptor family member X1 (NLRX1) and blood brain barrier (BBB)-permeable peptide, dNP2 ameliorates experimental autoimmune encephalomyelitis (EAE)." (PMID 32194859, 2020).
relapsing-remitting MS (3 papers, 2019 to 2022). "Nlrx1 mRNA expression is significantly increased in CD14+ PBMCs in relapsing-remitting MS patients, and the identification of rare NLRX1 mutations in MS patients, such as p.Lys172Asn, p.Glu192Ter, and p.Arg860Trp links NLRX1 genetic variants to the incidence of MS in humans." (PMID 34697412, 2022). "We quantified the expression of NLRX1 in peripheral blood mononuclear cells (PBMCs) from MS patients and found that PBMCs from relapsing-remitting MS (RRMS) patients express significantly higher levels of NLRX1 mRNA than healthy controls." (PMID 31525189, 2019). "In PBMCs of relapsing-remitting MS (RRMS) patients, NLRX1 levels are significantly higher compared to healthy controls." (PMID 33525671, 2021).
ulcerative colitis (3 papers, 2018 to 2024). An inflammatory bowel disease involving the mucosal surface of the large intestine and rectum. "In addition, NX‐13 activation of NLRX1 also showed resistance to oxidative stress and inflammation in human primary cells from ulcerative colitis patients, therefore becoming a promising NLRX1 agonist for treating IBD." (PMID 33682108, 2021). "With independent effects in epithelial and immune cells, NLRX1 may serve as a potent therapeutic target for Crohn’s disease (CD) and ulcerative colitis (UC) due to synergisms of NLRX1 signaling in epithelial and immune cells." (PMID 29535731, 2018).